YWHAH (tyrosine 3-monooxygenase/tryptophan 5-monooxygenase activation protein eta)
Description:
Adapter protein implicated in the regulation of a large spectrum of both general and specialized signaling pathways. Binds to a large number of partners, usually by recognition of a phosphoserine or phosphothreonine motif. Binding generally results in the modulation of the activity of the binding partner. Negatively regulates the kinase activity of PDPK1.
Synonyms: YWHA1
Tractability: Antibody: its Gene Ontology location is reachable by antibodies, with high confidence. PROTAC: ubiquitination databases record sites on it; its protein half-life has been measured.
Gene: Protein-coding gene on chromosome 22 (31,944,522 to 31,957,603, forward strand). Ensembl gene ENSG00000128245.
Subcellular location (Human Protein Atlas): Cytosol; Nucleoli rim; Nucleoplasm
Pathways (Reactome):
Disease: SARS-CoV-1 targets host intracellular signalling and regulatory pathways; SARS-CoV-2 targets host intracellular signalling and regulatory pathways
Cell Cycle: Chk1/Chk2(Cds1) mediated inactivation of Cyclin B:Cdk1 complex
Developmental Biology: Transcriptional and post-translational regulation of MITF-M expression and activity
Programmed Cell Death: Activation of BAD and translocation to mitochondria
Signal Transduction: RHO GTPases activate PKNs
Vesicle-mediated transport: Translocation of SLC2A4 (GLUT4) to the plasma membrane
Gene Ontology:
Molecular function: enzyme binding; identical protein binding; nuclear glucocorticoid receptor binding; protein binding; protein heterodimerization activity; sodium channel regulator activity; transmembrane transporter binding; insulin-like growth factor receptor binding; protein domain specific binding; actin binding
Biological process: glucocorticoid catabolic process; membrane depolarization during action potential; nuclear receptor-mediated glucocorticoid signaling pathway; positive regulation of DNA-templated transcription; regulation of sodium ion transport; substantia nigra development; intracellular protein localization; intracellular protein transport; negative regulation of dendrite morphogenesis; regulation of neuron differentiation; regulation of synaptic plasticity; presynaptic modulation of chemical synaptic transmission
Cellular component: extracellular exosome; mitochondrion; plasma membrane; cytoplasm; cytosol; intercalated disc; cerebellar granule cell to Purkinje cell synapse; glutamatergic synapse; presynapse; synapse
Genetic constraint (gnomAD): Loss-of-function variants: 6 observed, 19.78 expected, observed/expected ratio (o/e) 0.3, 90% interval 0.17 to 0.6. The upper end of that interval is the gene's LOEUF score, 0.6, which puts it in group 2 of 6, group 1 being the genes least tolerant of losing a copy. Missense variants: 173 observed, 293.13 expected, observed/expected ratio (o/e) 0.59, 90% interval 0.52 to 0.67. Synonymous variants: 135 observed, 117.64 expected, observed/expected ratio (o/e) 1.15, 90% interval 1 to 1.32.
Homologues: Orthologues: chimpanzee YWHAH (100% identical), guinea pig YWHAH (99% identical), mouse Ywhah (99% identical), rat Ywhah (99% identical), pig YWHAH (94% identical), tropical clawed frog ywhah (93% identical), dog YWHAH (91% identical), rabbit YWHAH (90% identical), zebrafish ywhah (85% identical), Drosophila melanogaster 14-3-3epsilon (63% identical). Paralogues in human: YWHAG (87% identical), YWHAB (76% identical), YWHAZ (75% identical), YWHAQ (70% identical), YWHAE (64% identical), SFN (62% identical).